OR2A2 (olfactory receptor family 2 subfamily A member 2)
Description:
Odorant receptor.
Synonyms: OR2A17P; OR2A2P; OST008; OR7-11
Tractability: Antibody: UniProt places it where antibodies can reach, with medium confidence; UniProt predicts a signal peptide or a membrane-spanning region; its Gene Ontology location is reachable by antibodies, with medium confidence.
Gene: Protein-coding gene on chromosome 7 (144,109,583 to 144,110,539, forward strand). Ensembl gene ENSG00000221989.
Subcellular location: Cell membrane
Pathways (Reactome):
Sensory Perception: Expression and translocation of olfactory receptors
Gene Ontology:
Molecular function: olfactory receptor activity; G protein-coupled receptor activity
Biological process: detection of chemical stimulus involved in sensory perception of smell; G protein-coupled receptor signaling pathway
Cellular component: plasma membrane; membrane
Genetic constraint (gnomAD): Missense variants: 375 observed, 388.09 expected, observed/expected ratio (o/e) 0.97, 90% interval 0.89 to 1.05. Synonymous variants: 163 observed, 155.07 expected, observed/expected ratio (o/e) 1.05, 90% interval 0.93 to 1.2.
Homologues: Orthologues: chimpanzee OR2A2 (98% identical), macaque OR2A2 (93% identical), dog OR2A2 (75% identical), mouse Or2a52 (73% identical), rat Or2a52 (72% identical). Paralogues in human: OR2A14 (75% identical), OR2A5 (70% identical), OR2A12 (69% identical), OR2A1 (64% identical), OR2A42 (64% identical), OR2A25 (60% identical), OR2A7 (58% identical), OR2A4 (58% identical), OR7C1 (43% identical), OR7C2 (43% identical), OR1E1 (43% identical), OR1E2 (43% identical), and 116 more.